TIMP1 (TIMP metallopeptidase inhibitor 1)
Diseases named in the same sentence as TIMP1 in open-access papers (continued):
Sharing a sentence is not in itself a finding about the gene and the disease.
cancer (continued). "High levels of MMP-13 in both cancer cells (p < 0.010) and peritumoral fibroblasts (p = 0.002), significantly correlated with the levels of TIMP-1 protein in the same specimens." (PMID 18373849, 2008). "Instead, we noted that MMP-13, both in cancer cells and peritumoral fibroblast cells, correlated with TIMP-1 and TIMP-2 (to a lesser extent)." (PMID 18373849, 2008). "This cell system represents a powerful tool for further studies of the antiapoptotic role of TIMP-1 in cancer, especially considering the quality of having a model system consisting of gene deficient cells and their identically genetic wild-type control." (PMID 17047657, 2006). "TIMP-1 mRNA has been detected in well-differentiated cancer cells, proliferated keratinocytes, and endothelial cells, and TIMP-1 overexpression has been observed in almost every case of HNSCC." (PMID 15291964, 2004). "Immunohistochemical study showed strong TIMP-1 staining in the stroma cells of advanced stages of carcinomas." (PMID 10098765, 1999). "Accordingly, the MMP-8/TIMP-1 ratio was reduced in individuals with incident cancer." (PMID 42162053, 2026). "Notably, in patients, clear correlations between elevated blood levels of TIMP-1 and progression of virtually all inflammatory diseases, including cancer, have been described." (PMID 40345589, 2025). "TIMP1, a matrix metalloproteinase inhibitor, exhibits context-dependent roles in cancer." (PMID 40145096, 2025). "Tissue inhibitor of metalloproteinases-1 (TIMP1), classically known for its inhibitory effects on matrix metalloproteinases (MMPs), has recently emerged as a multifunctional protein implicated in cancer progression." (PMID 41511313, 2025). "Previous studies have established TIMP1 as an oncogene that promoted malignant cancer phenotypes." (PMID 41187171, 2025). "TIMP1 was highly enriched in cluster 1, which mapped to the “invasive cancer” region." (PMID 40905789, 2025). "TIMP1 is highly expressed in most cancers and functions in a soluble form." (PMID 40224547, 2025). "Numerous studies consistently show significant TIMP1 upregulation across various cancers." (PMID 40963614, 2025). "Among these genes, the most overexpressed in platelet-educated cancer cells are those encoding proteins involved in cancer progression and metastasis, including SERPINE1 (358%), MMP2 (297%), MMP10 (214%), TIMP1 (187%), FN1 (166%), TMPRSS4 (146%) and RHOC (102%)." (PMID 40096084, 2025). "We discovered that TIMP1 expression in cancer tissue was correlated with T cell infiltration." (PMID 39789100, 2025). "Meta-analyses reveal plasma TIMP1 as an independent prognostic marker in certain cancers." (PMID 40963614, 2025). "In particular, high levels of N30 glycosylation site occupation (TIMP-1 N30glycHI) was identified as an indicator of an increased mortality risk of PC patients, corroborating the impact of N30 glycosylation site occupation of TIMP-1 on cancer progression." (PMID 40345589, 2025). "Clinically, elevated circulating TIMP-1 levels in cancer patients may serve as a biomarker for hepatic PMN formation and liver metastasis risk." (PMID 41463352, 2025). "Consistent with prior reports indicating the oncogenic role of TIMP1 in various cancers, our bioinformatic and clinical analyses confirmed that TIMP1 is overexpressed in CRC tissues and patient sera, and its elevated expression is independently associated with poor overall survival." (PMID 41511313, 2025). "This imbalance between MMPs and TIMP1 could contribute to the enhanced cancer progression observed in our study." (PMID 39124881, 2024). "TIMP1 was reported to function as an oncogene in different types of cancer." (PMID 39769169, 2024). "TIMP1 is known to inhibit MMPs and plays an active role in cancer repression." (PMID 39124881, 2024). "Furthermore, TIMP1 is implicated in the regulation of the PI3K/Akt/mTOR pathway, where it inhibits cancer cell apoptosis while promoting cancer cell migration and invasion." (PMID 39436133, 2024).
cancer (continued). "Notably, TIMP1 displayed a significant positive correlation with CD8A infiltration across most cancer types." (PMID 38777826, 2024). "TIMP-1 stimulates the growth of several cell types, including keratinocytes, aortic smooth muscle cells, skin epithelial cells, corneal epithelial cells, malignant cancer cells, and astrocytes." (PMID 39329731, 2024). "This leads to the conclusion that TIMP1 overexpression is beneficial for cancer development." (PMID 37509417, 2023). "Additionally, GSEA results showed that the high TIMP1 expression group was involved in many cancer signaling pathways." (PMID 37842645, 2023). "Furthermore, we investigated the expression profile of TIMP1 in various clinical variables across several GEO datasets, revealing its high expression in advanced clinicopathological stages and cancer tissues." (PMID 37688768, 2023). "Indeed, high levels of plasma TIMP-1 are a poor prognostic indicator for liver metastases and for the progression of gastric, colorectal, and pancreatic cancers." (PMID 37350937, 2023). "In-depth studies have shown that TIMP1 accelerates cell proliferation by activating YAP/TAZ in cancer, suggesting that the TIMP1-YAP/TAZ axis may be a potential new drug target for treating cancer patients." (PMID 36854781, 2023). "However, more recent inhibitors have been discovered through various means, which not only reduced TGM-2 but also other factors such as MMP9, TIMP1 and 2; TNF-α and β, which increases cancer cells’ susceptibility to chemotherapy and inflammation." (PMID 37509081, 2023). "However, the role of TIMP-1 in cancer is controversial because it can have both pro- and antitumoral effects." (PMID 36991043, 2023). "In several studies, TIMP1 expression was increased in cancer patients." (PMID 36854781, 2023). "It has other important functions in cancer as well: TIMP1 may stimulate cell growth, regulate angiogenesis, and inhibit apoptosis." (PMID 37091145, 2023). "TIMP1 is produced by cancer cells and has pleiotropic activities." (PMID 36768545, 2023). "TIMP1 is also recognized as a cancer-promoting factor due to its anti-apoptotic effects." (PMID 36800936, 2023). "Although M1-like TAMs show generally anti-tumoral effects, they may induce chronic inflammation, whereas the TIMP-1/IL-6 loop might foster STAT3 activation in cancer cells." (PMID 36291767, 2022). "The PROMISE score includes seven variables (chemotherapy, radiotherapy, hemoglobin, white blood cell count, C-reactive protein, ECOG performance status, and cancer type) in addition to pleural fluid tissue inhibitor of metalloproteinases 1 (TIMP1) for the biological PROMISE score." (PMID 35454064, 2022). "In fact, TIMP-1 released by CAFs promotes the migration and spread of cancer cells." (PMID 36555218, 2022). "The score includes clinical parameters (ECOG performance score, previous chemotherapy and radiotherapy, cancer type) and biological variables (white blood cell count, C-reactive protein, haemoglobin and serum levels of tissue inhibitor of metalloproteinases-1, TIMP-1)." (PMID 36465336, 2022). "Additionally, TIMP1 expression in fibroblasts again emerges in stage III when cancer has become decidedly metastatic." (PMID 35565326, 2022). "We then assessed whether TIMP1EV is selectively enriched in CRC-EVs and whether TIMP1EV levels are directly affected by cellular TIMP1 levels in cancer cells." (PMID 35140332, 2022). "A high expression of TIMP1 has a significant correlation with a poor prognosis of cancer." (PMID 35559040, 2022). "The high expression of TIMP1 confers poor prognoses in several types of cancers including GBM." (PMID 35647198, 2022). "For example, TIMP-1 has been shown to interact with several MMPs and the matrix-degrading properties of the MMPs, which could play a fundamental role in the spread of cancer." (PMID 36230852, 2022). "The overexpression of TIMP1 promotes cancer cell invasion and angiogenesis during BC development." (PMID 36499502, 2022).
cancer (continued). "Previous studies indicated that as a part of ECM, TIMP1 could led to accelerated differentiation and hypertrophy of adipocytes, which contributed to the pathogenesis of cancer." (PMID 34356118, 2021). "We found that ITGB5 promotes cancer, while TIMP1 and TMEM176B suppress cancer." (PMID 34109215, 2021). "Studies have shown that CCNA2, HAS2 and TIMP1 can regulate the cell cycle of cancer cells." (PMID 33619234, 2021). "Moreover, CBD has been found to reduce MMP secretion and activity, as well as upregulation of MMP inhibitors such as TIMP-1 in various types of cancer development." (PMID 34691360, 2021). "Besides, HCC cells-secreted tissue inhibitor of metalloproteinase 1 (TIMP-1), an endogenous inhibitor for MMPs, has been reported to accelerate cancer progression by initiating the transformation of liver fibroblasts into CAFs." (PMID 33292459, 2020). "In a number of studies, the expression of TIMP1 was increased in cancer patients." (PMID 32566650, 2020). "TIMP-1 reduces expression of MMP-2 in impairing cancer migration." (PMID 33187385, 2020). "The Ca2+ increase culminates with triggering of several mechanisms such apoptosis (via mitochondrial transmembrane potential alterations), an increase of intracellular reactive oxygen species (ROS), autophagy, cell cycle arrest, or inhibition of cancer cells invasion through up-regulation of TIMP-1." (PMID 31979368, 2020). "Since our study demonstrated higher expression of TIMP-2 in high-grade serous ovarian tumours, we used normal secretory Fallopian tube and cancer cell lines that expressed relatively more TIMP-2 than TIMP-1 or TIMP-3, to investigate in vitro the cellular functions of TIMP-2 by transient knockdown." (PMID 33023532, 2020). "In-depth studies have revealed that TIMP1 accelerates cell proliferation by activating YAP/TAZ in cancer, suggesting that the TIMP1-YAP/TAZ axis may be a novel potential drug target for the treatment of cancer patients." (PMID 32566650, 2020). "Total content of MMP-14, MMP-15, and TIMP-1 in control human urinary bladder and its cancers." (PMID 32049862, 2020). "TIMPs, including the 4 founding members TIMP1/2/3/4, have been verified to function as antagonists against the proteolytic effect from MMPs by stabilizing the basal membrane and restricting the invasion and metastasis of cancer cells." (PMID 31937294, 2020). "The upregulation of TIMP-1 contributes to inhibition of cancer cell invasion." (PMID 32349289, 2020). "Interestingly, proteins such as Mucins, TIMP1, and Laminin B1 were specifically enriched in EVs that increased cancer cell invasion." (PMID 33225939, 2020). "Interestingly, an IPA analysis showed that different regulated genes were positively associated with the invasion and migration process in cancer cells: VCAN, SPARC, IL6, MMP14, IL4R, ICAM, TIMP1 and IGF2." (PMID 32848147, 2020). "Accordingly, TIMP1 is considered as a prognostic marker for cancer progression and metastasis." (PMID 32526853, 2020). "In thisrespect, the reduction of TIMP-1 gene expression by TVSE may be considered apositive influencer of cancer growth and metastasis." (PMID 33152052, 2020). "Indeed, at very low concentrations (3 μM), CBD induced intracellular adhesion molecule 1 (ICAM-1) and TIMP1 levels, decreasing cellular migration and increasing cancer cell lysis." (PMID 31979368, 2020). "The elimination of LOXL2 in cancer cells decreases its invasion and TIMP-1 levels." (PMID 33419373, 2020). "To determine whether exogenous TIMP1 mRNA delivered by platelet has a biological function in cancer cells, we analyzed the TIMP1 protein level in HT29 cells and Caco-2 cells." (PMID 31639773, 2019). "TIMP1 also stimulates cancer cell proliferation and apoptosis." (PMID 31639773, 2019). "Our hypothesis was that the expression and concentration of MMP-9 and TIMP-1 are associated with TNM and histological differentiation of cancer." (PMID 31143300, 2019).
cancer (continued). "Over the past year, more and more studies have focused on the influence of TIMP1 in cancers." (PMID 30867991, 2019). "Indeed, TIMP-1 has been studied extensively in cancer and is therefore of significant interest for determining how metastases develop without producing pain." (PMID 31616247, 2019). "Collectively, the data presented here suggest that cisplatin-induced TIMP-1 release from cancer but not non-cancer cells is a crucial event that causes a reduction in the angiogenic capability of endothelial cells." (PMID 30344920, 2018). "Elevated serum and tissue levels of TIMP1 have been found in cancer patients." (PMID 30414611, 2018). "Although TIMP-1 levels were significantly raised at the time of diagnosis in cancer patients compared to healthy controls, the absolute increase observed in the absence of biliary obstruction was relatively small compared to those seen in the presence of obstruction." (PMID 29394913, 2018). "This hypothesis is supported by published data that TIMP1 is involved in inhibiting apoptosis by suppressing BAX in cancer cells, bone marrow stromal cell line, and mesangial cells." (PMID 29742163, 2018). "Moreover, TIMP1 has been shown to be overexpressed in multiple cancer types and acts as a therapeutic target for GC and other cancers." (PMID 30568862, 2018). "Jaundice also impaired the use of TIMP-1 as a prognostic marker in cancer patients." (PMID 29394913, 2018). "Interestingly, TIMP1, one of the metallopeptidase inhibitors, was significantly over-expressed in cancers as compared to normal lungs." (PMID 29137669, 2017). "Thus, we believe that TIMP-1 plays a role in the suppression of cancer cell migration by interacting with CD82." (PMID 28030805, 2017). "All MMPs and TIMP-1 exhibited elevated levels in cancer patients." (PMID 29207990, 2017). "Moreover, the β1,6-branch also regulates the function of other cancer-related molecules such as matriptase, tissue inhibitor of metalloproteinase-1 (TIMP-1) and E-cadherin." (PMID 27136596, 2016). "In this study we investigated the potential use of TIMP-1 antibody in cancer therapy." (PMID 27130446, 2016). "Importantly, we clarified the pivotal role of HAS2, which probably led to disruption in the expression of MMP1 and TIMP1 and consequently promoted cancer progression." (PMID 27884164, 2016). "Moreover, knockdown of FAAH by siRNA was shown to confer decreased cancer cell invasiveness and increased TIMP-1 expression." (PMID 26930716, 2016). "On the other hand, TIMP-1 also possesses non MP-related cell stimulating and pro-angiogenesis functions that have since precluded its development as a viable therapeutic agent against cancers." (PMID 26308720, 2015). "In contrast, TIMP1 levels were increased in malignant tumors compared to the normal ovary." (PMID 26579497, 2015). "Intriguingly, recent studies have shown that TIMP-1 plays a dual role in cancer progression." (PMID 25909286, 2015). "Tissue inhibitors of metalloproteinases (TIMPs) are the major cellular inhibitors of the MMPs, but interestingly, elevated levels of the tissue inhibitor TIMP-1 is found in several cancer types and elevated levels of TIMP-1 and -2 have been correlated with poor prognosis and cancer progression." (PMID 24670365, 2014). "It is likely, therefore, that altered patterns of miR expression may also facilitate the differential expression of gelatinase B/MMP-9 and TIMP-1 in malignant tumours." (PMID 24473089, 2014). "However, additional further studies are needed to establish the mechanisms for the inhibitory effects on cancer invasion by up-regulation of TIMP-1 and TIMP-2." (PMID 24018886, 2013). "CD63 may then serve as an important therapeutic target against the cancer types with elevated stroma TIMP-1 levels." (PMID 24143225, 2013).
cancer (continued). "However, recent studies reported a controversial role of ICAM-1, that is, its activation is necessary to induce the tissue inhibitor of matrix metalloproteinases-1 (TIMP-1) and a subsequent decrease in the extent of cancer cell invasiveness." (PMID 23573150, 2013). "Expression of TIMP-1 was increased in cancer tissue in prostate." (PMID 24015777, 2013). "In addition, we showed that TIMP-1 is up-regulated in the cancer stroma compared to their normal counterparts." (PMID 24143225, 2013). "TIMP-1 is a potent biological inhibitor of MMPs including MMP-9 (gelatinase B), a metalloproteinase that has been implicated as a potential therapeutic target in a wide variety of inflammatory and vascular diseases and in cancer." (PMID 23185522, 2012). "Overall these results suggest that PEGylated TIMP-1 exhibits improved potential for development as an anti-cancer recombinant protein therapeutic, and additionally may offer potential for clinical applications in the treatment of other diseases." (PMID 23185522, 2012). "This discrepancy could be explained by the production of TIMP-1 from other sources than cancer cells, e.g. by stroma cells." (PMID 20459644, 2010). "Moreover, several studies have found a correlation between TIMP-1 protein levels in blood or tumour tissue obtained from various cancer types (breast, esophageal, gastric, renal, colorectal and non-small cell lung carcinoma) and prognosis." (PMID 20459644, 2010). "TIMP-1 activity in tumour tissue may therefore play an essential role in the progression of a malignant tumour." (PMID 20459644, 2010). "Similarly, E-cadherin has been reported to transcriptionally regulate a variety of integrins and matrix metalloproteases (MMP1, MMP2, MMP3, MMP14 and TIMP-1) in other cancer models." (PMID 19257890, 2009). "Additionally, the presence of significant non-cancer in the samples (as indicated by TIMP1 Western) or that of multiple CD cancer cell types (e.g., CD10+), especially in the higher Gleason grades, was also problematic." (PMID 20021671, 2009). "However, in recent years, TIMP-1 has been recognised as a multifunctional protein, playing a complex role in cancer." (PMID 17047657, 2006). "Since chemotherapy works by inducing apoptosis in cancer cells, we raised the hypothesis that TIMP-1 promotes resistance against chemotherapeutic drugs." (PMID 17047657, 2006). "It is proposed that plasma measurements of TIMP-1 may have value in the management of cancer patients." (PMID 10408859, 1999). "Although TIMP1 can be antitumorigenic and antimetastatic functions in cell lines or mice, clinical findings showed that TIMP1 was consistently elevated in cancerous tissues as well as in blood, and clearly correlated with poor prognosis of most cancer patients." (PMID 38408082, 2024). "While existing studies indirectly suggest that these biological functions are associated with cancer proliferation and metastasis, they do not specifically address their relationship with TIMP1." (PMID 37842645, 2023). "It remains unclear whether aberrant AS of TIMP1 is also involved in other cancer types." (PMID 37735421, 2023). "In addition, it may be extremely possible to diagnose cancers by precisely analyzing the expression of TIMP-1 in exosomes." (PMID 36230852, 2022). "TIMP1 may be a pluripotent protein with important functions for cancers." (PMID 36158681, 2022). "Hence, the establishment of a TIMP-1/IL-6 loop to increase STAT3 activity may depend on cancer type and CAF subtype." (PMID 36291767, 2022). "Notably, TIMP-1 is of crucial significance in cancer invasion and metastasis." (PMID 33628641, 2021). "Therefore the detection of CEA or TIMP1 as cancer biomarkers is crucial for cancer diagnosis, or more specifically, for the monitoring of patients who suffer from cancer which produce CEA after and before getting chemotherapy, surgery, radiation, or combination of all." (PMID 32230808, 2020).